HSPA9 (heat shock protein family A (Hsp70) member 9)
Diseases named in the same sentence as HSPA9 in open-access papers (continued):
Sharing a sentence is not in itself a finding about the gene and the disease.
even-plus syndrome (7 papers, 2015 to 2025). "In this review, variants of the HSPA9 have been shown in this study to be recessive in the cases of EVEN-PLUS syndrome (EVPLS, MIM #616854) with microtia." (PMID 38594752, 2024). "Recessive compound heterozygous or homozygous variants in HSPA9 cause EVEN-PLUS syndrome, which is characterized by skeletal phenotypes resembling CODAS, with additional findings." (PMID 33171986, 2020). "The two HSPA9 variants initially linked to EVEN-PLUS syndrome are found in the nucleotide binding domain of HSPA9." (PMID 33171986, 2020). "In the same year, EVEN-PLUS syndrome (EVPLS) was revealed to be caused by HSPA9 gene mutations (c.376C>T and 383A>G or 882-883delAG), which lead to amino acid substitution Arg126Trp, Tyr128Cys, or early termination, respectively." (PMID 37288145, 2021). "For example, MAN2C1 is associated with congenital disorder of deglycosylation 2 (MIM #619775), GPHN with molybdenum cofactor deficiency C (MIM #615501), LRP2 with Donnai–Barrow syndrome (MIM #222448), and HSPA9 with Even-plus syndrome (MIM #616854)." (PMID 40282865, 2025).
melanoma (7 papers, 2011 to 2024). A malignant, usually aggressive tumor composed of atypical, neoplastic melanocytes. "In vemurafenib-resistant BRAF-mutant melanoma cells, HSPA9 depletion triggers cell death in a MEK/ERK- and ANT/CypD-dependent manner, indicating that HSPA9 is an effective target in drug-resistant tumors." (PMID 39261452, 2024). "Along these lines, other members of the HSP70 family like the mitochondrial-localized member GRP75 (HSPA9) are also emerging targets for melanoma." (PMID 35187538, 2021). "Under standard conditions (37 °C), melanoma cells were characterized by a high level (>0.04) of HSPD1 (HSP60), HSPA8 (HSP70), and HSP90AB1 (HSP90), and a medium level (0.02–0.04) of HSPB1 (HSP27), HSPA9 (HSP70), and AHSA1 (HSP90)." (PMID 37886980, 2023).
Alzheimer disease (6 papers, 2013 to 2025). A progressive, neurodegenerative disease characterized by loss of function and death of nerve cells in several areas of the brain leading to loss of cognitive function such as memory and language. "Previously, we showed that decreased HSPA9 expression is associated with neurodegenerative diseases, such as Alzheimer’s disease (AD) and Parkinson’s disease (PD)." (PMID 37170364, 2023). "GRP75/Mortalin (also known as HSPA9) has also been implicated in the pathogenesis of other neurodegenerative conditions, including Parkinson’s disease and Alzheimer’s disease, suggesting that it, too, may be contributing directly to SMA pathogenesis." (PMID 24134804, 2013). "We take recent work linking HSPA9 to roles in the control of peroxisomal function and neuronal stress detection and its downregulation in animal models of Alzheimer’s disease and patient’s brains as a suggestion that this could be a relevant protein for the control of HD." (PMID 35628660, 2022).
liver cancer (6 papers, 2014 to 2025). An epithelial or non-epithelial malignant neoplasm that arises from the liver. "Metastasis and early tumor recurrence have been associated with Hspa9 overexpression in liver cancer." (PMID 38138960, 2023). "According to these findings, the combined inhibition of Hsp90 and Hspa9 was found to dramatically reduce tumor growth in a liver cancer xenograft model, and the Hsp90 inhibitor was also found to promote the expression of Hspa9." (PMID 38138960, 2023). "HSPA9 has been reported to be upregulated in liver cancer and pancreatic cancer." (PMID 34765552, 2021).
cardiac hypertrophy (4 papers, 2021 to 2025). "Therefore, abnormal regulation of Mfn1 and Hspa9 might have detrimental effects on the normal function of the heart and potentially induce cardiac hypertrophy." (PMID 37221368, 2023).
colorectal cancer (4 papers, 2018 to 2024). A primary or metastatic malignant neoplasm that affects the colon or rectum. "HSPA9 was found to be a key gene in determining clinical outcomes in resected colorectal cancer patients, hinting at differing expression levels in tumor stem cells compared to normal stem cells in the digestive tract." (PMID 38732562, 2024). "Additionally, circulating HSPA9 levels are elevated in colorectal cancer patients and correlated with worse prognosis, indicating that HSPA9 is a useful prognostic biomarker." (PMID 39261452, 2024). "Interestingly, human protein atlas indicates that the level of HSPA9 (mortalin) can be unfavorable (breast cancer) or favorable (colorectal cancer)." (PMID 35859897, 2022).
glioblastoma (4 papers, 2019 to 2026). The most malignant astrocytic tumor (WHO grade IV). "In glioblastoma, HSPA9 interacts with OMA1 zinc metallopeptidase (OMA1) and induces mitophagy." (PMID 41491061, 2026).
leukemia (4 papers, 2013 to 2024). A malignant (clonal) hematologic disorder, involving hematopoietic stem cells and characterized by the presence of primitive or atypical myeloid or lymphoid cells in the bone marrow and the blood. "This could be explored in the context of leukemia and lymphomas as metabolic rewiring is modulated by HSP90 and HSPA9, promoting the production of large amounts of needed ATP." (PMID 36765939, 2023).
neuroblastoma (4 papers, 2011 to 2024). Neuroblastoma (NB) is the most common solid, extracranial childhood tumor. "Thus, we investigated whether HSPA9 affected primary ciliogenesis in SH-SY5Y neuroblastoma cells." (PMID 37170364, 2023).
pancreatic cancers (4 papers, 2014 to 2024). "A significant decrease in viability was observed in simultaneous XPO1 + HSPA9 or RUVBL1/2 targeting in comparison with normal fibroblasts and typical chemotherapy protocols used for colon, lung or pancreatic cancers." (PMID 39217152, 2024).
thyroid cancer (4 papers, 2012 to 2022). "HSPA9 is associating with survival and proliferation of thyroid carcinoma cells." (PMID 34412642, 2021).
Congenital Sideroblastic Anemia (3 papers, 2021 to 2022). "A genetic screen of patients with congenital sideroblastic anemia has revealed several mutations in the long arm of chromosome 5, specifically in the HSPA9 gene which codes for the mitochondrial Hsp70 protein." (PMID 35252210, 2022).
COVID-19 (3 papers, 2023 to 2025). A disease caused by infection with severe acute respiratory syndrome coronavirus 2. "However, rs1042665 HSPA9 was associated with an increased risk of severe COVID-19 in the group with normal fresh fruit and vegetable intake (risk allele C, OR = 1.67, 95% CI 1.14–2.46, p = 0.009, pperm = 0.009 (pbonf = 0.02))." (PMID 41009536, 2025). "Specifically, the polymorphic variants rs1136141 and rs1461496 HSPA8, rs1042665 HSPA9, rs7189628 DNAJA2, rs910652 HSPA12B, rs6457452 HSPA1B and rs1043618 HSPA1A are associated with alerted risk of severe COVID-19." (PMID 41009536, 2025). "We therefore concluded that HSP90AA1, HSPA9, and SRSF1 are pivotal genes in the co-morbidity of COVID-19 and ICM and have considerable diagnostic value." (PMID 37047484, 2023). "For example, the inhibitor developed for the polymerase PARP-1 and HSPA9 can be used against COVID-19." (PMID 37047484, 2023). "Finally, in our study, we identified the SNP rs1042665 HSPA9 as a risk allele for severe COVID-19 across groups with normal physical activity levels and adequate intake of fresh fruit and vegetables." (PMID 41009536, 2025). "Our analysis of the cis-eQTL effects of the SNP rs1042665 HSPA9 suggests a complex interplay of gene regulation involving KDM3B, ETF1, FAM53C, KLHL3, and DNAJC18, potentially contributing to COVID-19 severity." (PMID 41009536, 2025). "In this study, HSP90AA1, HSPA9, and SRSF1 were identified as markers for the co-pathogenesis of COVID-19 and ICM." (PMID 37047484, 2023). "We identified HSP90AA1, HSPA9, and SRSF1 as markers for the co-pathogenesis of ICM and COVID-19, and showed that co-pathogenesis of ICM and COVID-19 may be related to angiogenesis." (PMID 37047484, 2023). "Despite the failure of docking with SRSF1, the docking of vindesine and ON-01910 with HSP90AA1 and HSPA9 tentatively validated the feasibility of these drugs binding to the hub genes, indicating that vindesine and ON-01910 may be disease-specific agents of ICM and COVID-19." (PMID 37047484, 2023).
gastric cancer (3 papers, 2014 to 2025). A primary or metastatic malignant neoplasm involving the stomach. "With this interaction characterized, we then explored the regulatory relationship between TFRC and HSPA9 by modulating HSPA9 expression in gastric cancer cells." (PMID 40946428, 2025). "This study provides a comprehensive model of how artesunate leverages TFRC stabilization and HSPA9 inhibition to induce ferroptosis in gastric cancer cells." (PMID 40946428, 2025). "RBBP6, DCTPP1, and HSPA9 were observed to be primarily expressed in the cytoplasm and nuclei of gastric cancer cells." (PMID 25379943, 2014). "HSPA9 and HSPA4 were concluded to be associated with the invasion and metastatic activity of gastric cancer." (PMID 25379943, 2014). "In this study, we demonstrate for the first time that artesunate induces ferroptosis in gastric cancer cells through its regulation of TFRC, specifically by stabilizing TFRC expression and inhibiting HSPA9-mediated lysosomal degradation of TFRC." (PMID 40946428, 2025).
lung adenocarcinoma (3 papers, 2021 to 2024). A carcinoma that arises from the lung and is characterized by the presence of malignant glandular epithelial cells. "Using immunohistochemistry, the expression levels of PSMB6, HSPA9, DUT, CDK7, and PLK1 were found to be higher in lung adenocarcinoma tissues of patients, while the expression of FOLR2 was low, which was consistent with survival prediction." (PMID 34721732, 2021).
lung carcinoma (3 papers, 2015 to 2022).
medullary thyroid carcinoma (3 papers, 2019 to 2026). "HSPA9 was also reported to promote proliferation of medullary thyroid carcinoma cells through regulating mitochondrial bioenergetics." (PMID 41491061, 2026). "We previously reported that upregulation of mortalin (HSPA9/GRP75), the mitochondrial HSP70 chaperone, facilitates tumor cell proliferation and survival in human medullary thyroid carcinoma (MTC), proposing mortalin as a novel therapeutic target for MTC." (PMID 31027376, 2019).
Obesity (3 papers, 2022 to 2025). Accumulation of substantial excess body fat. "Obesity also consistently altered 5 proteins in DMBA-exposed mice, including HNRNPC, HNRNPD, HSPA9, RPL36A, and KCTD12." (PMID 39910959, 2025).
sideroblastic anemia (3 papers, 2022 to 2024). "In contrast, however, deficiencies in proteins responsible for ISC transfer, such as GLRX5, HSPA9, and HSCB, have been tightly linked with sideroblastic anemia phenotypes." (PMID 38757931, 2024).
thymic carcinoma (3 papers, 2022 to 2024). Thymic carcinoma (TC) is a type of thymic epithelial neoplasm characterized by a high malignant potential. "There is a positive correlation between the expression levels of LOXL1AS1 and HSPA9, and there is a negative association between miR-525–5p and HSPA9 in thymoma and thymic carcinoma." (PMID 39136001, 2024). "Therefore, the overexpression of HSPA9, resulting from the overexpression of LOXL1AS1, inhibits apoptosis and promotes proliferation and invasion in both thymoma and thymic carcinoma." (PMID 39136001, 2024).
viral infection (3 papers, 2018 to 2026). "Indeed, 1,10 phenanthroline is a high-affinity chelator for divalent metal ions such as Fe2+ and Zn2+, which are essential elements in many cellular processes, and HSPA9 is a multipotent chaperone regulating cellular processes ranging from viral infection to neurodegeneration." (PMID 36978861, 2023). "Eight proteins (GPT2, HSPA9, MAPK1, PDIA3, PDIA6, PSMC5, TALDO1, and ATP5B) were predicted/known to be involved in viral infection." (PMID 29404200, 2018). "The change in abundance of eight of the targeted proteins (GPT2, HSPA9, MAPK1, PDIA3, PDIA6, PSMC5, TALDO1, and ATP5B) was predicted to collectively inhibit viral infection (pathway analysis)." (PMID 29404200, 2018). "Analysis using IPA software suggested that eight of the targeted proteins (ATP5B, GPT2, HSPA9, MAPK1, PDIA3, PDIA6, PSMC5, and TALDO1) were involved in virus infection and their lower protein abundance may inhibit viral infection." (PMID 29404200, 2018).
anemia (2 papers, 2016 to 2024). A reduction in the number of red blood cells, the amount of hemoglobin, and/or the volume of packed red blood cells. "Zebrafish with a homozygous point mutation in Hspa9 present phenotypically with a variety of abnormalities including severe anemia, defects in erythroid differentiation, and elevated apoptosis." (PMID 38508444, 2024). "Our findings not only indicate that reduced levels of HSPA9 may contribute to anemia observed in del(5q)-associated MDS patients, but also provide new insights into potential mechanisms of anemia." (PMID 38508444, 2024). "Thus, HSPA9/mortalin may also be a potential target to treat anemia in del(5q) MDS patients, although the simultaneous loss of multiple genes on del(5q) likely contributes to the complex phenotypes observed in MDS." (PMID 38508444, 2024). "To study the role of HSPA9 in regulating erythroid maturation, we knocked down the expression of HSPA9 in human CD34+ hematopoietic progenitor cells grown in erythroid differentiation media to explore the mechanism of anemia observed in del(5q) MDS patients." (PMID 38508444, 2024). "In this study we show that the proximal del(5q) candidate gene HSPA9 regulates erythroid maturation in human CD34+ cells, suggesting HSPA9/mortalin may be a potential target to treat anemia in del(5q) MDS patients by reactivating its expression from the residual wild-type nondeleted allele." (PMID 38508444, 2024).
heart failure (2 papers, 2020 to 2022). Inability of the heart to pump blood at an adequate rate to meet tissue metabolic requirements. "Underexpression of HSPA8 and HSPA9 will disrupt cardiomyocyte homeostasis and interfere with critical cellular functions by small aggregates of proteins, which finally contributes to heart failure and hereditary heart diseases." (PMID 32595699, 2020).
hyperthyroidism (2 papers, 2023 to 2024). Overactivity of the thyroid gland resulting in overproduction of thyroid hormone and increased metabolic rate. "HSPA9 is a multipotent stress response chaperone protein induced by metabolic stress, glucose deprivation, calcium ionophores, thyroid hormone treatment, hyperthyroidism, ionizing radiation, and several cytotoxins." (PMID 37170364, 2023).
intracerebral haemorrhage (2 papers, 2019 to 2022). "A recent study has clarified that overexpression of HSPA9 prevents inflammation in a rat model of intracerebral haemorrhage through inhibition of inflammatory cytokines such as TNF-α, IL-β, Bax, and increased Bcl-2 levels." (PMID 35258800, 2022).
myeloid malignancies (2 papers, 2015 to 2018). "Heat shock 70-kDa protein 9 (HSPA9) has been localised to chromosome 5, band q31, which is a region frequently deleted in some kinds of myeloid neoplasms." (PMID 26569224, 2015). "Deletion of the HSPA9 locus (5q31.1) is a frequent finding in myeloid malignancies." (PMID 29507682, 2018).
triple-negative breast carcinoma (2 papers, 2019 to 2021). An invasive breast carcinoma which is negative for expression of estrogen receptor (ER), progesterone receptor (PR), and human epidermal growth factor receptor 2 (HER2). "Our findings present PCDHGB7 and HSPA9 as potential therapeutic targets for further studies in attempts to overcome chemoresistance in triple-negative breast cancer." (PMID 31379979, 2019).
cognitive decline (1 paper, 2022). "The bioinformatics data together indicate that upregulation of SERPINA1, VCP, PRNP, CIP2A, HSPA9, and UQCRC2 and downregulation of IGFBP3, CRHBP, PEPD, and GUSB were correlated to cognitive decline in T2DM patients." (PMID 36506101, 2022).
colitis (1 paper, 2024). Inflammation of the colon. "Nevertheless, the connection between HSPA9 and the regulation of oxidative stress through SOD1 enhances our understanding of the role of HSPA9 in regulating mitochondrial ROS and colitis symptoms." (PMID 38467701, 2024). "To investigate HSPA9 deficiency in colitis, we employed a DSS-induced mouse model, which is a widely used chemical for experimental colitis mouse models." (PMID 38467701, 2024). "Taken together, these results indicate that HSPA9 reduction further exacerbates colitis, leading to a more severe phenotype of DSS-induced colitis by influencing the macrophages activation." (PMID 38467701, 2024). "In a dextran sodium sulfate-induced colitis mouse model, the downregulated HSPA9 exacerbates colitis symptoms, including increased immune cell infiltration, elevated proinflammatory cytokines, decreased tight junctions, and altered macrophage polarization." (PMID 38467701, 2024). "Taken together, our study provides insights into the impact of downregulated HSPA9 in DSS-induced colitis, demonstrating its influence on macrophage activation, oxidative stress regulation, and mitochondrial fission." (PMID 38467701, 2024). "Based on this observation, we investigated the connection between HSPA9 and colitis using an HSPA9 knockdown mouse model." (PMID 38467701, 2024). "This increment, along with the earlier results, suggests that HSPA9 downregulation possibly exacerbates colitis by enhancing infiltration and triggering macrophage activation via the STAT3 pathway." (PMID 38467701, 2024). "In DSS-induced colitis, reduced HSPA9 expression was observed in WT mice, suggesting a relationship between HSPA9 and disease progression." (PMID 38467701, 2024). "In conclusion, our research demonstrated the critical role of HSPA9 in the development and progression of colitis." (PMID 38467701, 2024). "Examination of the microarray data from the Gene Expression Omnibus (GEO) on National Center for Biotechnology Information (NCBI) revealed that, compared with healthy controls, patients with colitis demonstrated downregulation of HSPA9 expression." (PMID 38467701, 2024). "To investigate this, we studied HSPA9-downregulated mice (HSPA9 heterozygous mice) in a dextran sodium sulfate (DSS)-induced colitis model, which is known to have similarities with human UC." (PMID 38467701, 2024). "Moreover, we observed a consistent pattern of downregulated HSPA9 expression in datasets of patients with colitis." (PMID 38467701, 2024). "Based on the known functions of HSPA9, we considered the possibility that HSPA9 reduction may contribute to the exacerbation of colitis and investigated its relevance." (PMID 38467701, 2024). "Building on the known function of HSPA9 in mitochondrial dynamics and the established connection between mitochondrial dysfunction and the progression of colitis, we investigated the impact of HSPA9 reduction on colitis." (PMID 38467701, 2024). "An enhanced understanding of the relationships among HSPA9 expression, mitochondrial dynamics, macrophage activation, and ROS regulation in colitis provide valuable insights that may facilitate innovative therapeutic strategies." (PMID 38467701, 2024). "Thus, we investigated the relationship between HSPA9 and colitis through a DSS-induced colitis mouse model." (PMID 38467701, 2024). "Although the specific role of HSPA9 in inflammation has not been thoroughly investigated, its potential impact on mitochondrial dynamics and oxidative stress suggests a possible connection to colitis pathology." (PMID 38467701, 2024).